FLT1 (fms related receptor tyrosine kinase 1)
Diseases named in the same sentence as FLT1 in open-access papers (continued):
Sharing a sentence is not in itself a finding about the gene and the disease.
psoriasis (5 papers, 2019 to 2023). An autoimmune condition characterized by red, well-delineated plaques with silvery scales that are usually on the extensor surfaces and scalp. "Conditional loss of VEGFR-1/Flt1 or neuropilin-1 (Nrp1) in epidermal cells can reverse the psoriasis-like phenotype of VEGFA overexpressing mice, suggesting the role of blocking the VEGFA/Flt1/Nrp1 axis in psoriasis." (PMID 38203230, 2023). "Skin-infiltrating pDCs express VEGFR-1/Flt1 and VEGFR-2/Flk1, and VEGFA initiates psoriasis inflammatory cascade reaction by stimulating pDCs." (PMID 38203230, 2023). "Keratinocyte-specific deletion of Flt1 or Nrp1 diminished VEGFA-induced psoriasis, suggesting that VEGFA/Flt1/Nrp1 axis has an essential epidermal autonomous function in the pathogenesis of psoriasis." (PMID 35075118, 2022).
bladder cancer (4 papers, 2022 to 2025). "The higher expression of FLT1 might contribute to the pro-angiogenic activity of PGF in bladder cancer." (PMID 39628692, 2024). "As the results derived from CellphoneDB are based on the expression profiles of ligands and receptors 29, the expression level of FLT1 in the endothelium of bladder cancer might be higher than that of KDR." (PMID 39628692, 2024). "As the results derived from CellphoneDB were based on the expression levels of ligands and receptors in distinct cell types, this phenomenon could be attributed to the expression levels of FLT1 and KDR in the endothelial cells of bladder cancers." (PMID 39628692, 2024).
cognitive decline (4 papers, 2021 to 2026). "Within the prefrontal cortex, higher expression of these four genes (VEGFB, FLT1, PGF, and FLT4) was associated with more rapid cognitive decline and higher pathology burden." (PMID 39641382, 2025). "Prefrontal cortex expression of multiple VEGF genes, including ligand genes VEGFB and PGF and receptor genes FLT1 and FLT4, were associated with a more rapid rate of cognitive decline late in life, with VEGFB and FLT4 also associated with cognitive scores closest to death." (PMID 31332262, 2021). "When we expanded our analyses to brain tissues we observed that VEGFB, FLT1, PGF, and FLT4 all appear to contribute to the progression of AD pathology and cognitive decline." (PMID 39641382, 2025).
multiple myeloma (4 papers, 2016 to 2023). "HMGB1 also has a novel interaction with the MPM gene, FLT1, shown to be involved in the migration of multiple myeloma cells by associating with β1 integrin, and mediating PKC activation." (PMID 33916178, 2021).
placental disorders (4 papers, 2015 to 2023). "For instance, we found hyperacetylation of regions near HK2, FLT1, and LEP, previously reported to be upregulated in other placental disorders, and hypoacetylation of regions near CH2 and CDLN1, which are involved in growth and endothelial cell-to-cell adhesions." (PMID 29983832, 2018).
prostate tumor (4 papers, 2015 to 2024). "Regarding vascular endothelial growth factor receptor-1 (Vegfr1/Flt1) transcription in prostate tumor samples we observed a down-regulation in TRAMP.eJag1OE and an up-regulation in TRAMP.eJag1cKO." (PMID 26213336, 2015). "Interestingly, tumor-cell expression of FLT1 has been reported in ovarian, pancreatic, and prostate tumors, suggesting that FLT1 signaling could potentially drive PARPi resistance in these cancers as well." (PMID 38956205, 2024).
retinal degeneration (4 papers, 2013 to 2024). Degeneration of the retina. "VEGFA and FLT1 targeted therapies are being explored as both pro- and anti-angiogenic therapies for several indications including retinal degeneration, cancer, pre-eclampsia, and neuromuscular diseases." (PMID 38842166, 2024). "Although there are several inherited retinal degeneration models with changes in RPE/photoreceptors where CNV does not develop, it is theoretically possible that pathological disturbances in RPE or photoreceptors due to Flt-1 knockout may themselves contribute to the development of CNV." (PMID 23795287, 2013).
skin tumor (4 papers, 2012 to 2019). "Using the K5-SOS transgenic mouse model, in which mice develop skin tumors spontaneously or after a skin wound, it has been shown that epidermal tumor cells of K5-SOS transgenic mice express high levels of VEGF and its receptors Flt1 and Nrp1." (PMID 24563633, 2014).
thrombosis (4 papers, 2016 to 2025). "Among them, mutations in ABCA13, FLT1, NRP1, SWAP70 and SLC15A4 are strongly associated with immunity or proliferation, whereas mutations in VWF, SELP and EPHB2 are associated mainly with thrombosis." (PMID 39671267, 2024).
ulcer (4 papers, 2013 to 2023). "We analyzed the mRNA expressions of platelet-derived growth factor (PDGF), transforming growth factor-β (TGF-β), vascular endothelial growth factor (VEGF), and Fms-like tyrosine kinase-1 (FLT-1) in the ulcer tissue." (PMID 25538944, 2014).
wet age-related macular degeneration (4 papers, 2022 to 2025). "Several studies found that the KDR and FLT1 genotypes may represent predictive determinants of efficacy in ranibizumab-treated neovascular age-related macular degeneration (nAMD) patients." (PMID 35893809, 2022).
breast adenocarcinoma (3 papers, 2010 to 2013). "We hypothesized that treatment of MBA-MD-231 human breast adenocarcinoma xenograft tumors with vivo-VEGFR1_MOe13 would result in increased levels of soluble Flt-1 and a subsequent decrease in neovascularization and tumor regression." (PMID 22438952, 2012). "Thus, we sought to determine whether expression of the VEGFR1_MOe13 in MCF7 and MBA-MD-231 breast adenocarcinoma cells would increase soluble FLT-1 levels." (PMID 22438952, 2012). "Morpholino oligomers targeting the VEGFR1 mRNA exon/intron 13 junction promote production of soluble FLT-1 over membrane bound FLT-1, resulting in suppression of lesional volume in laser induced CNV and breast adenocarcinoma." (PMID 22438952, 2012).
choriocarcinoma (3 papers, 2020 to 2021). An aggressive malignant tumor arising from trophoblastic cells. "Choriocarcinoma, a highly vascular tumourderived from trophoblasts, displays epigenetic silencing of FLT1 via promoter hypermethylation." (PMID 33465324, 2021). "Epigeneticsilencing of FLT1 blocks expression of thisnegative regulator, thereby facilitating angiogenesis in choriocarcinoma." (PMID 33465324, 2021). "Different from other VEGF receptors, FLT1, downregulated in parathyroid cancer, was considered as a tumor suppressor gene in choriocarcinoma." (PMID 33910638, 2021). "Because the HRE motif 5′-(A/G)CGTG-3′ also contains one CpG dinucleotide, we investigated the effects of hypoxic stimulation on FLT1 expression and sFLT1 production in the three choriocarcinoma cell lines treated with 5azadC." (PMID 32041578, 2020). "We found that sFLT1 production is inhibited by FLT1 gene silencing via hypermethylation of its promoter in choriocarcinoma cell lines and primary choriocarcinoma tissue." (PMID 32041578, 2020). "The methylation status of FLT1 has also been reported in other cancer cell lines and tissue samples besides choriocarcinoma." (PMID 32041578, 2020). "Recently, we reported that hypoxia-inducible factor-2α (HIF-2α) mediates the hypoxia-induced up-regulation of FLT1 gene expression in the BeWo, JAR and JEG-3 three choriocarcinoma cell lines." (PMID 32041578, 2020). "Our results suggest that HRE motifs in FLT1 were methylated, suppressing the binding of HIF-α in all three choriocarcinoma cell lines, as sFLT1 production was enhanced by hypoxic stimulation after 5azadC treatment." (PMID 32041578, 2020).
Cirrhosis (3 papers, 2011 to 2025). A chronic disorder of the liver in which liver tissue becomes scarred and is partially replaced by regenerative nodules and fibrotic tissue resulting in loss of liver function. "In the initial validation cohort, plasma levels of FLT1 were significantly higher in PoPH subjects as compared to non-PoPH cirrhosis." (PMID 37558836, 2023). "In this study, we observed differential gene expression of BMPR2, ESR1, and FLT1 genes in livers from patients with PoPH relative to non-PoPH cirrhosis, patterns supported by immunohistochemical staining of human liver tissue." (PMID 37558836, 2023). "In particular, BMPR2 expression appeared to be reduced, and both ESR1 and FLT1 expression appeared to be increased, in PoPH peri-central hepatocytes as compared to non-PoPH cirrhosis liver tissue." (PMID 37558836, 2023). "FLT1 levels discriminated PoPH from non-PoPH cirrhosis in the initial cohort (AUC of 0.817, 95% CI 0.727–0.907), even after adjusting regression models for several clinical covariates (age, sex, race/ethnicity, BMI)." (PMID 37558836, 2023). "As PoPH nuclei demonstrated a pattern of differential gene expression involving the BMPR2, ESR1, and FLT1 genes, we then sought to validate this pattern of gene expression using immunohistochemistry staining of human liver tissue from PoPH, non-PoPH cirrhosis, and normal liver tissue samples." (PMID 37558836, 2023). "PoPH samples demonstrated relatively more intense staining for both the ESR1 and FLT1 proteins, and relatively less staining for the BMPR2 protein, in the region surrounding liver central veins (the “peri-central” zone) relative to non-PoPH cirrhosis tissue." (PMID 37558836, 2023).
dementia (3 papers, 2018 to 2025). Loss of intellectual abilities interfering with an individual's social and occupational functions. "CSF levels of YKL-40, ICAM-1, VCAM-1, IL-15, and Flt-1 were increased during the preclinical, prodromal, and dementia stages of AD." (PMID 30054439, 2018). "Finally, higher levels of CSF YKL-40, ICAM-1, and Flt-1 increased risk of development of AD dementia in patients without dementia." (PMID 30054439, 2018).
depression (3 papers, 2011 to 2024). "Individuals with depression that were homozygous for the G allele of the FLT1 polymorphism rs7993418 were associated with lower symptom severity (p-value = 0.040)." (PMID 36559251, 2022). "Afterwards, we assessed whether genetic polymorphisms of VEGF and its receptors, KDR and FLT1, are associated with depression and severity of symptoms, considering the presence of early life stress in these associations (ELS)." (PMID 36559251, 2022). "In the present study, we aimed to assess whether plasma levels of VEGF, KDR, and FLT1 were associated with depression risk, symptoms intensity, and suicide attempts." (PMID 36559251, 2022). "To examine the association between the VEGF pathway and depression, we genotyped polymorphisms and measured the plasma concentrations of VEGF, KDR, and FLT1 proteins." (PMID 36559251, 2022).
Gestational Diabetes Mellitus (3 papers, 2017 to 2026). "Reduction in Flt-1 expression with no change in VEGF or kinase insert domain receptor (KDR) expression was observed in gestational diabetes." (PMID 36078079, 2022).
metabolic syndrome (3 papers, 2017 to 2024). A cluster of metabolic risk factors for CARDIOVASCULAR DISEASES and TYPE 2 DIABETES MELLITUS. "Our analysis identified four essential genes—SPP1, IGF1, CD44, and FLT1—that serve as potential molecular links between Alzheimer’s and metabolic syndrome." (PMID 38809924, 2024). "PIK3R2, STRA8, FLT1, DMRT1, FGF22, NR5A2, and FLT genes were up-regulated in metabolic syndrome after exercise." (PMID 37053002, 2023). "PIK3R2, STRA8, FLT1, DMRT1, FGF22, NR5A2, and FLT were up-regulated and PRDM14, POU5F1, and KDR were down-regulated in metabolic syndrome after exercise." (PMID 37053002, 2023). "Consequently, we have identified FLT1, SPP1, CD44, and IGF1 as the critical genes shared among the clusters in the PPI network of AD and metabolic syndrome." (PMID 38809924, 2024).
periodontitis (3 papers, 2017 to 2025). An acute or chronic inflammatory process that affects the tissues that surround and support the teeth. "However, it has been described that the Flt-1 gene is highly upregulated in periodontitis-associated fibroblasts." (PMID 40800007, 2025).
pulmonary hypertension (3 papers, 2009 to 2024). Increased pressure within the pulmonary circulation due to lung or heart disorder. "Angiogenic factors are likely to be involved in the initiation of endothelial cell dysfunction and the development of pulmonary hypertension VEGF and its receptors flt-1 and flk-1 are expressed in the plexiform lesions in the lungs of patients with severe PH." (PMID 19426547, 2009).
rectal cancer (3 papers, 2011 to 2021). A primary or metastatic malignant neoplasm that affects the rectum. "In the irradiated rectal cancer secretome there was again a significant inverse correlation between skeletal muscle and Flt-1 (r = −0.7182, p = 0.01) and VEGF-D (r = −1, p = 0.01)." (PMID 33540635, 2021). "While in the rectal cancer TME, CD80 levels on DCs correlated positively with Flt-1 and inversely with IL-27." (PMID 33540635, 2021).
sarcoidosis (3 papers, 2009 to 2022). Sarcoidosis is a multisystemic disorder of unknown cause characterized by the formation of immune granulomas in involved organs. "Our major finding was an increase of the receptor Flt-1 at protein level in IPF in comparison with sarcoidosis." (PMID 20169144, 2009). "Meanwhile, the “hsa04060: cytokine–cytokine receptor interaction’ pathway, including the CCL4, CSF1R, CXCR4, FLT1, and IL7 genes, could be highly associated with immune regulation and is strongly suspected to be involved in the pathogenesis of sarcoidosis." (PMID 35860586, 2022).
chorioamnionitis (2 papers, 2021). A morphologic finding indicating inflammation of the fetal sac membranes. "In rat models of pre-eclampsia and chorioamnionitis, treatment with an anti-Flt-1 mAb improved infant lung structure and function, including increased vascular density and alveolarization, and prolonged neonatal survival." (PMID 33898634, 2021). "Both VEGF and neuropilins (but not Flt-1 and KDR2) were upregulated after stimulation with IL-1β, which provided an explanation for how an intra-amniotic infection might increase the risk of placental abruption." (PMID 34205566, 2021).
cognition impairment (2 papers, 2021 to 2022). "At the same time, a higher expression of VEGFB, FLT4, FLT1, and PGF in the prefrontal cortex was related to the stronger cognitive impairments in patients indicating impaired neural network function." (PMID 33672819, 2021).
diabetic foot ulcers (2 papers, 2023 to 2025). "Of note, the hsa-HLA-DRB1/miRNA_12118/FLT-1 axis was identified, which may have a crucial role in the development of diabetic foot ulcers." (PMID 40419622, 2025).
Gorham syndrome (2 papers, 2015 to 2023). "In addition, this case shows that propranolol can be administered safely and has a significant therapeutic effect on Gorham syndrome by reducing circulating VEGF-A rather than by changing VEGF-C or Fms-like tyrosine kinase-1 (FLT-1) levels." (PMID 37215116, 2023). "Furthermore, this case demonstrates that Propranolol can be safely administered and has striking therapeutic efficacy as a single agent in Gorham’s syndrome by decreasing circulating VEGF-A but not by modifying VEGF-C or FLT-1 levels." (PMID 26238450, 2015). "In view of this difference, the authors explained that lymphoid malformation and Gorham syndrome are not the same clinical entity and proposed that Gorham syndrome depends on VEGF-A, not VEGF-C or FLT-1." (PMID 37215116, 2023). "Our results suggest that, despite pronounced lymphangiogenesis, Gorham’s syndrome seems to be dependent on VEGF-A and not on VEGF-C or FLT-1." (PMID 26238450, 2015).
Hydrocephalus (2 papers, 2016 to 2025). Hydrocephalus is an active distension of the ventricular system of the brain resulting from inadequate passage of CSF from its point of production within the cerebral ventricles to its point of absorption into the systemic circulation. "Levels of the angiogenesis proteins VEGF, VEGF-C, VEGF-D, and bFGF were significantly elevated at 1 day post-injury in the CSF, while the angiogenesis protein Flt-1 was elevated up to 5 days post-injury in the CSF when compared to hydrocephalus controls." (PMID 40427506, 2025). "aSAH patients presented significantly elevated levels of Flt-1 in the CSF at both timepoints when compared with hydrocephalus controls." (PMID 40427506, 2025).
keloid (2 papers, 2022 to 2025). An irregularly shaped, elevated mark on the skin caused by deposits of excessive amounts of collagen during wound healing. "Ultimately, 7 hub genes—EDN1, NTF3, VCAM1, ADRB2, BDNF, F3 and FLT1—were identified, all of which had interaction scores above 0.70, indicating their potential roles in keloid formation and progression." (PMID 40051702, 2025). "The heatmap illustrates the differential expression of these 13 OSRDEGs between keloid and normal skin tissues, where F3, FOXL2, EDN1, and NTF3 show higher expression in keloid tissues, while BDNF, FLT1, VCAM1 and ADRB2 are more highly expressed in normal skin." (PMID 40051702, 2025).
liposarcoma (2 papers, 2010 to 2016). A usually painless malignant tumor that arises from adipose tissue. "We conclude that upregulation of FLT1 in MLS/RCLS is an indirect downstream effect of the liposarcoma fusion oncogene FUS-DDIT3 and that FLT1 is expressed as a nuclear protein both in MLS/RCLS lipoblasts and in normal adipocytes." (PMID 20515481, 2010).
lupus (2 papers, 2020 to 2024). "As systemic lupus erythematosus (SLE) is a severe autoimmune inflammatory disease and abnormal activation of CD4+ T cells plays predominant roles in the pathogenesis of SLE, we detected the expression of VEGFB and FLT1 in CD4+ T cells from patients with SLE." (PMID 39145452, 2024).
meningioma (2 papers, 2021 to 2025). A generally slow growing tumor attached to the dura mater. "Additionally, there were eight kinases that were not significantly differently expressed between meningioma and VS present in the macrophages (LCK, PDGFRB, FGFR1, FLT1, CSK, MEK, MAP2K2, and ERBB2)." (PMID 41437121, 2025).
mesothelioma (2 papers, 2013 to 2024). A usually malignant and aggressive neoplasm of the mesothelium which is often associated with exposure to asbestos. "It has been shown that the expression of VEGFR-1/Flt-1, VEGFR-2/KDR, Nrp-1 and Nrp-2 remains unchanged during the malignant transformation of MCs (e.g. mesothelioma)." (PMID 23585849, 2013).
parasite infection (2 papers, 2021 to 2023). "Using publicly available bulk RNA-seq and single-cell RNA-seq datasets from two different parasite infection models, we determined that the nematode infection-induced alternative macrophage polarization was linked to elevated Flt1 mRNA level and repressed Vegfa expression." (PMID 37215144, 2023). "Nevertheless, these findings raised the possibility that the alternatively polarized macrophage-produced FLT1 can contribute to the defense response of the host against the parasite infection through VEGFA neutralization and angiogenesis inhibition." (PMID 37215144, 2023).
rosacea (2 papers, 2025). A chronic erythematous skin disorder that affects the face. "Specifically, the expression of FLT1 and TLR2 genes is significantly elevated in rosacea patients." (PMID 39823143, 2025).
thyroid (2 papers, 2024 to 2025). "Integration with conventional DEG signatures revealed a functionally cohesive module, with C1QA/B/C, FLT1, TEK, PDGFRB, SPP1, and HLA-DPB1 emerging as central regulators of thyroid irAEs." (PMID 41221294, 2025).
type 1 diabetes (2 papers, 2017 to 2018). "Here, we investigated whether the VEGF-A inhibitor soluble FLT-1 (sFLT-1; also known as soluble VEGFR-1) can reduce renal complications, including albuminuria and mesangial matrix expansion, in a mouse model of type 1 diabetes and pre-existing kidney damage." (PMID 28620823, 2017).